C3 (complement C3)
Diseases named in the same sentence as C3 in open-access papers (continued):
Sharing a sentence is not in itself a finding about the gene and the disease.
ANCA-associated vasculitis (11 papers, 2021 to 2025). "Many recent studies demonstrated that C3 levels are correlated to patient and kidney survival in ANCA-associated vasculitis as well." (PMID 35874697, 2022). "In different diseases, C3 is activated through distinct pathways—predominantly via the alternative pathway in ANCA-associated vasculitis, characterized by prominent local synthesis and deposition, whereas in SLE the classical pathway is the major driver, leading to systemic complement consumption." (PMID 41187099, 2025). "Additionally, the downstream cleaved protein of C3, known as C5a, has become a promising target for ANCA-associated vasculitis (AAV) treatment." (PMID 33627173, 2021). "Although C3 levels were not decreased in our patient, the literature shows C3c is only deposited in approximately one-third of ANCA-associated vasculitis patients." (PMID 39310478, 2024). "Several studies have shown that low serum C3 levels, but not C4 levels, can estimate severe ANCA-associated vasculitis (AAV), and can predict poor renal outcome at diagnosis." (PMID 35491890, 2022).
crescentic glomerulonephritis (11 papers, 2016 to 2025). A histopathologic term for a pattern of diseases characterized by extensive crescent formation in the glomeruli; patients present clinically with rapid deterioration of renal function, and possible progression to end-stage renal failure within weeks or months. "Focal necrotizing and crescentic glomerulonephritis with mesangial proliferative changes and C3 deposits (active COVID-19 infection-associated)." (PMID 40429298, 2025). "The biopsy demonstrates focal necrotizing (1 of 16) and crescentic glomerulonephritis (1 of 16) associated with C3 deposits in the mesangium and capillary walls." (PMID 40429298, 2025). "In contrast, smaller amounts of C4 deposition were detected compared to those of C3 deposition in the kidney of MPO/PR3-ANCA-positive patients with crescentic glomerulonephritis." (PMID 37833884, 2023). "A renal biopsy showed crescentic glomerulonephritis with C3 deposition in the glomerular capillary wall, and immunostaining for anti-Treponema pallidum antibody was weakly positive in some interstitium and one glomerulus." (PMID 38129918, 2023). "A kidney biopsy revealed necrotising crescentic glomerulonephritis with linear deposits of IgG, IgM and C3 along the glomerular basement membrane, confirming a recurrence of anti-GBM disease." (PMID 33639869, 2021). "The biopsy showed crescentic glomerulonephritis with c3 deposition in mesangium and basement membrane." (PMID 33777557, 2021). "Histologic analysis of the specimens showed crescentic glomerulonephritis in 5 cases, and immunofluorescence studies showed faint C3 and IgM expression in 3 cases." (PMID 32702934, 2020). "Three patients with crescentic glomerulonephritis had positive immunofluorescence (one with positive IgM, IgG, IgA, C3, and C1q deposits, one with modest positive mesangial IgM, IgG, and C3, and another with positive IgG and C3 deposits) while four patients had negative immunological fluorescence." (PMID 39767180, 2024). "Her renal biopsy showed granular depositions of IgG/IgA antibodies and C3 complement in mesangial tissue with crescentic glomerulonephritis and fibrinoid necrosis, which is not commonly expected in AAV patients." (PMID 36755329, 2023). "A subsequent renal biopsy revealed crescentic glomerulonephritis and interstitial nephritis with negative immunofluorescence (IgA (+/−), IgG (−), C3 (−), C4 (−), C1q (−), and Flb (−)), which is consistent with ANCA-associated pauci-immune glomerulonephritis." (PMID 32702934, 2020).
dementia (11 papers, 2016 to 2025). Loss of intellectual abilities interfering with an individual's social and occupational functions. "Comparison of complement proteins between the two subgroups showed that C3 and FI were significantly lower in the dementia group, though whether this is cause or consequence of the pathology is unclear." (PMID 36149090, 2023). "Similar findings were observed in dementia patients, where C3 expression was elevated in brain tissue and cerebrospinal fluid; C3b levels in the brains of asymptomatic frontotemporal dementia carriers showed an inverse correlation with frontal lobe volume." (PMID 40539508, 2025). "Previous studies have revealed that complement C3 levels increase with age in humans, monkeys, and mice; elevated C3 expression is also observed in the brains of dementia patients." (PMID 40539508, 2025). "Individuals with Down Syndrome (DS) and dementia had significantly lower plasma levels of C3 and factor I compared with those without dementia." (PMID 38505993, 2024).
inflammatory bowel disease (11 papers, 2018 to 2025). A spectrum of small and large bowel inflammatory diseases of unknown etiology. "High C3 levels could also be seen in patients with inflammatory bowel disease, which is associated with chronic inflammation." (PMID 37893046, 2023). "Patients with inflammatory bowel disease had a higher expression of C3 in their intestinal tissue, and this is thought to contribute to chronic inflammation and tissue injury." (PMID 40698088, 2025). "The level of C3 mRNA was upregulated in inflammatory bowel disease (IBD) and Crohn’s disease (CD) patients." (PMID 35743302, 2022). "Complement C3, α2-macroglobulin, Inflammatory bowel disease, Biomarker, Inflammatory cytokines, Clinical chemistry." (PMID 33851052, 2021). "In support of our findings, anti-TNF drugs have been previously reported to inhibit the classical complement pathway in inflammatory bowel disease, and to decrease serum levels of C3 and C4 in PsA and RA." (PMID 31335881, 2019). "It is first found that the C3 mRNA expression is significantly upregulated in the inflamed mucosa of patients with inflammatory bowel disease." (PMID 30186855, 2018). "Likewise, C3 levels were significantly upregulated in the mucosae of patients with inflammatory bowel disease." (PMID 34722636, 2021). "Patients with inflammatory bowel diseases (IBD), such as ulcerative colitis (UC) and Crohn’s disease (CD), show enhanced catabolism and deposition of C3 as well as circulating C3 conversion products at the site of inflammation." (PMID 35105928, 2022).
osteoarthritis (11 papers, 2011 to 2026). A noninflammatory degenerative joint disease occurring chiefly in older persons, characterized by degeneration of the articular cartilage, hypertrophy of bone at the margins and changes in the synovial membrane. "Interestingly, the complement system has been implicated in cartilage degradation, and C3 has been found to be aberrantly increased in synovial fluids from individuals with osteoarthritis." (PMID 24889399, 2014). "C3, C4, and Fb have been found in various tissues in osteoarthritis patient joints, and in vitro cultures have shown that chondrocytes can produce C3a and C5a." (PMID 35955822, 2022). "Complement activation in PsA has also been investigated at the joint level: in the synovial fluid from PsA patients, C3 levels were higher compared to samples from RA subjects and those with osteoarthritis, even though C3c split product was lower in PsA than RA." (PMID 35242041, 2022). "Levels of C3a, a marker of the central complement system C3 processing, were higher in RRV-infected patients than in patients with noninflammatory osteoarthritis." (PMID 24069610, 2013).
Parkinson disease (11 papers, 2020 to 2026). A progressive degenerative disorder of the central nervous system characterized by loss of dopamine producing neurons in the substantia nigra and the presence of Lewy bodies in the substantia nigra and locus coeruleus. "Previous MR studies on Alzheimer’s disease suggest potential causal associations with BIN1, CCL27, C3, CD33, CD4 T cells, GDF-15 and SVEP1, whereas MR studies on Parkinson’s disease suggest a potential causal association with GPNMB, IL-6 and MIP1b." (PMID 37118290, 2022). "In degenerative conditions such as AD, ALS, Huntington's disease (HD), and Parkinson's disease (PD), overactivation of components like C1q, C3, and C5a drives aberrant synaptic pruning, fuels microglia-mediated neuroinflammation, and in some cases induces dopaminergic neuron loss." (PMID 40896413, 2025).
staphylococcus aureus infection (11 papers, 2016 to 2025). An infectious process in which the bacteria Staphylococcus aureus is present. "The genes C1QA, C1QB, C1QC, C1S, C3, and C4A in cluster 2 were predominantly enriched in top ten pathways including Staphylococcus aureus infection, pertussis and complement and coagulation cascades." (PMID 37409113, 2023). "C3 was involved in complement and coagulation cascades and Staphylococcus aureus infection pathways." (PMID 38087257, 2023). "In vivo data demonstrated that during Staphylococcus aureus infection, NETosis requires C3, and that C3aR played a greater role as compared with C5aR in NET formation." (PMID 26996437, 2016). "Furthermore, C3 is involved in the regulation of the staphylococcus aureus infection pathway, which subsequently triggers an acute inflammatory response in both human and animal bodies." (PMID 38671889, 2024). "Besides, Complement C3 (C3) participated in legionellosis and Staphylococcus aureus infection signaling pathway." (PMID 29226137, 2017). "KEGG pathway: The bar chart of the KEGG pathways related to the set of genes showed that most genes were involved in Staphylococcus aureus infection (KRT32, C3, KRT38, and KRT37) and the estrogen signaling pathway (KRT32, KRT38, and KRT37)." (PMID 37900279, 2023). "Among which, we also performed the PPI network of several DEGS including C3, HLA-DRB5, ICAM1 and HLA-DRB1, ITGAM, and CFD that involved in the staphylococcus aureus infection signaling pathway." (PMID 30186855, 2018). "HLA-DRB1, HLA-DRB5, C3, and ICAM were significantly involved in staphylococcus aureus infection." (PMID 30186855, 2018). "Target DEGs of differentially expressed miRNAs were significantly enriched in staphylococcus aureus infection involving four DEGs (HLA-DRB1, HLA-DRB5, C3, and ICAM), which suggested that inflammation may be a factor for STC." (PMID 30186855, 2018).
Atrophy (10 papers, 2012 to 2025). Any weakening or degeneration, especially through lack of use. "This study analyzed the impact of the C3 inhibitor pegcetacoplan on photoreceptor degeneration outside of RPE-atrophy using data from the randomized FILLY phase-2 trial." (PMID 36284220, 2022). "In line with their findings, in the present study, we clearly showed that patients with higher grade mesangial deposition of C3 had worse histologic findings such as mesangial hypercellularity and tubular atrophy/interstitial fibrosis than those with lower grade deposition." (PMID 22792353, 2012).
hepatocellular carcinoma (10 papers, 2011 to 2025). A malignant tumor that arises from hepatocytes. "This investigation aimed to create a new nomogram based on complement C3 to forecast 1-, 3-, and 5-year overall survival (OS) rates in patients with early-stage hepatocellular carcinoma (HCC) exhibiting microvascular invasion (MVI) post-curative surgery." (PMID 40052130, 2025). "Znf202 overexpression in mouse hepatoma cells mhAT3F2 resulted in downregulation of members of the Apoe/c1/c2 and Apoa1/c3/a4 gene cluster." (PMID 23469003, 2013). "However, research into the effectiveness of complement C3 as a serological marker for forecasting the prognosis of hepatocellular carcinoma remains notably scarce." (PMID 40052130, 2025). "Moreover, the nuclear translocation of C3b was also found in hepatocellular carcinoma cells, a dominant tissue/cell type responsible for C3 production." (PMID 37291119, 2023). "In addition, expression of the transcription factor C/EBP-β, which induces C3 promoter activity, was reduced in immortalized human hepatocytes and human hepatoma cells (Huh7) that were either infected with cell culture-adapted HCV or transfected with HCV-NS5A." (PMID 29910796, 2018). "Interestingly, IL-6 enhances C3 transcription and secretion in a rat hepatoma cell line." (PMID 32244854, 2020). "Studies using co-culture of NK cells (NK3.3) with human hepatoma cells (Huh7.5) expressing HCV core or NS5A protein revealed a significantly increased synthesis of complement C4 and C3 via increased specific transcription factors." (PMID 34335607, 2021). "C3 has also been reported to activate the renal renin–angiotensin system via induction of the EMT of the nephrotubulus in mice, while inhibition of C3aR/C5aR attenuated the proliferation of hepatocellular carcinoma via inhibition of the EMT." (PMID 34439277, 2021).
leukemia (10 papers, 2018 to 2023). A malignant (clonal) hematologic disorder, involving hematopoietic stem cells and characterized by the presence of primitive or atypical myeloid or lymphoid cells in the bone marrow and the blood. "Following chemotherapy 2 fragments generated from C4 protein (C4a, C4d) and C3 protein (C3g or C3dg) were not only significantly lower than during overt leukemia but also lower than in the post-chemotherapy PBP." (PMID 36109804, 2022). "In further support of such a mechanism, we found that human leukemia cells lines express endogenous mRNA for C3 and C5 and express several elements of the inflammasome complex (not shown)." (PMID 31231394, 2019). "Thus, activation of the ComC in leukemia/lymphoma patients (e.g., as the result of accompanying microbial infections or chemotherapy-induced sterile inflammation) and release of C3 and C5 cleavage fragments could be ameliorated by inhibition of p38 MAPK or upregulation of HO-1." (PMID 31231394, 2019). "The extent of C3 activation and C3 splitting were correlated with disease severity while immunoglobin level remained consistently high and not varied much between different types of leukemia." (PMID 33193442, 2020).
rheumatic diseases (10 papers, 2012 to 2025). "When used, as they are in the rheumatic disease, their value often lies in looking for a decrease in the measured C3 and C4 to assess the level and pathway of any ongoing activation of complement leading to consumptions." (PMID 34434189, 2021). "C3, C4, and C1q measurements have also been utilized historically in testing for the rheumatic disease and PIDs." (PMID 34434189, 2021). "Similar to ESR and CRP, other parameters recognized as activity measures in rheumatic diseases, such as decreased C3 and C4 or increased fibrinogen concentration did not correlate with the occurrence of CTS in the studied group." (PMID 38969943, 2024). "In one study of 304 SLE patients, 285 patients with other rheumatic diseases, and 205 healthy individuals, the AUC for the presence of SLE was 0.79 ± 0.02 with antibodies to double-stranded DNA, 0.73 ± 0.02 with complement C3, and 0.72 ± 0.02 with complement C4." (PMID 39052098, 2024).
Splenomegaly (10 papers, 2012 to 2025). Abnormal increased size of the spleen. "By the age of 24 years, her laboratory tests showed reduced levels of C3 and C4 complement fractions, and an abdominal ultrasound scan confirmed the presence of splenomegaly." (PMID 39873967, 2025). "Age, purpura, splenomegaly, serum levels of C3, Scr, cryocrit." (PMID 40799649, 2025). "In the present study, GILZ-/- mice showed little evidence of splenomegaly, ENA, IgG or C3 in glomeruli of younger mice, or inflammatory cytokine expression, and for these reasons we did not assess the kidneys of GILZ-/- for glomerular injury." (PMID 33889157, 2021).
Anxiety (9 papers, 2021 to 2026). Intense feelings of nervousness, tension, or panic often arise in response to interpersonal stresses. "Interestingly, levels of complement subunit 3 (C3), an antimicrobial factor that has been implicated in anxiety, were upregulated in the amygdala of Chd8+/ΔIEC mice." (PMID 37783686, 2023). "Thus, enhanced C3 signaling pathway activation in chronic inflammatory disorders such as SLE may contribute to anxiety-induced synapse loss, chronic stress, and alteration in synaptic connection in the PFC." (PMID 37884917, 2023). "We then investigate the exploratory or anxiety-like behaviors during the open-field test in C3-/-, C3aR-/-, and WT mice infected by S. aureus." (PMID 40294039, 2025). "Regarding anxiety, the initial data showed a robust correlation (p < 0.01) with positivity for LA (0.330) and anti-ribosome P antibodies (0.312, p < 0.05), as well as low C3 (0.263, p < 0.05) and low C4 (0.293, p < 0.05), and anti-SM antibodies (0.247, p < 0.05)." (PMID 38540098, 2024). "Furthermore, the complement C3- C3aR also related to anxiety behavior." (PMID 36106141, 2022). "In MDD patients, C3 levels were found to be related to Hamilton Rating Scale for Anxiety (HAMA) scores, although other clinical factors were not related to complement components and CRP." (PMID 37884917, 2023).
autoimmune hemolytic anemia (9 papers, 2017 to 2026). Autoimmune hemolytic anemia (AIHA) is an autoimmune disorder in which various types of auto-antibodies are directed against red blood cells causing their survival to be shortened and resulting in hemolytic anemia. "A direct antiglobulin test (DAT) was positive, with IgG and C3 antibodies found bound to red blood cells, which combined with elevated hemolysis parameters was consistent with the diagnosis of autoimmune hemolytic anemia." (PMID 39677070, 2024). "Moreover, other novel treatments can be considered in future research and trials such as pegcetacoplan, a C3 inhibitor of the alternative complement pathway, that was used and showed a promising result in autoimmune hemolytic anemia." (PMID 41035870, 2025). "At SLE diagnosis, pleuritis (19.2% vs. 5.6%; p = 0.035), autoimmune hemolytic anemia (AIHA) (38.5% vs. 18.6%; p = 0.037), and C3 hypocomplementemia (80.8% vs. 55.4%; p = 0.014) were significantly more common in the hemangioma group." (PMID 42207195, 2026). "The direct antiglobulin test (DAT) was strongly positive (IgG +4, C3 +3), confirming warm autoimmune hemolytic anemia (AIHA)." (PMID 41281042, 2025). "The binding of C3 fragments to RBCs, characteristic of various autoimmune hemolytic anemias, had never been found in PNH and it has emerged as a novel phenomenon in PNH patients on eculizumab." (PMID 28629435, 2017).